ESR1 (estrogen receptor 1)
Diseases named in the same sentence as ESR1 in open-access papers (continued):
Sharing a sentence is not in itself a finding about the gene and the disease.
hepatitis B (3 papers, 2021 to 2023). "Variant ESR1 expression is predominant in male patients with hepatitis B-associated HCC and is predictive of worse survival." (PMID 34881186, 2021). "Decreased expression of this gene was significantly related to a high liver damage score, pathological invasion of the intrahepatic portal vein, tumor size and hepatitis B virus infection, showed that ESR1 gene is a candidate protective gene in HCC." (PMID 34671598, 2021). "The core of subnetwork 2 is ESR1, CASP3, and IL6, which are closely related to the TNF signalling pathway and the hepatitis B pathway." (PMID 36818231, 2023).
knee osteoarthritis (3 papers, 2014 to 2021). "Though ESR-1 polymorphism has been previously linkedwith the development of knee osteoarthritis, we found nocorrelation with disease severity, clinical features orradiographic appearance in patients presenting for total kneereplacement by allele differences." (PMID 25347522, 2014). "Previous reports have highlighted ESR-1 polymorphism as arisk factor of knee osteoarthritis." (PMID 25347522, 2014).
melasma (3 papers, 2024 to 2025). "Recent network pharmacology and molecular dynamics studies investigating potential melasma treatments have highlighted the involvement of estrogen receptors (ESR1 and ESR2) and the prolactin signaling pathway in melasma pathogenesis." (PMID 41154805, 2025). "For example, specific Cassipourea metabolites have shown significant binding effects on ESR1 and ESR2, suggesting their potential as modulators in melasma treatment." (PMID 41154805, 2025).
mesothelioma (3 papers, 2021 to 2025). A usually malignant and aggressive neoplasm of the mesothelium which is often associated with exposure to asbestos. "A meta‐analysis has further revealed that the APC gene is significantly hypomethylated in mesothelioma, while CDH1, ESR1, miR‐34b/c, PGR, RARβ, SFRP1, and WIF1 are significantly hypermethylated." (PMID 40904706, 2025). "A recent systematic review and quantitative meta-analysis of DNA methylation in mesothelioma found both significantly hypomethylated genes (APC) and hypermethylated genes (CDH1, ESR1, miR34b/c, PGR, RATO, SFRP1, and WIF1)." (PMID 38297314, 2024).
migraine headache (3 papers, 2014 to 2024). "As a result, we recognized totally 7 possible causing genes (CALCA, TGFBR2, TNF, ESR1, EDNRA, KCNK18, and MTHFR) of headache in the top 10 genes." (PMID 24991551, 2014).
myeloid leukemia (3 papers, 2023 to 2025). A clonal proliferation of myeloid cells and their precursors in the bone marrow, peripheral blood, and spleen. "ESR1, encoding estrogen receptor alpha (ERα), has been identified as a central protein in various diseases, including myeloid leukemia, where it serves as a pivotal communication hub." (PMID 39625993, 2024).
oligodendroglioma (3 papers, 2009 to 2021). A well-differentiated (WHO grade II), diffusely infiltrating neuroglial tumor, typically located in the cerebral hemispheres. "Other genes hypermethylated in oligodendrogliomas include the tumor suppressors CDKN2A, CDKN2B and RB1, as well as DAPK1 (death-associated protein kinase 1), ESR1 (estrogen receptor 1), THBS (thrombospondin 1) and TIMP3 (tissue inhibitor of metalloproteinase 3)." (PMID 19333441, 2009).
Peritoneal Fibrosis (3 papers, 2023 to 2025). Disorder characterized by a wide range of structural changes in PERITONEUM, resulting from fibrogenic or inflammatory processes. "Targeting the ESR1/H19/VEGFA pathway pharmacologically can attenuate high glucose-induced peritoneal fibrosis." (PMID 40918510, 2025). "In the second study, tamoxifen reduced H19 levels by decreasing the ESR1-mediaed transcription of H19 in an experimental system of high glucose-induced peritoneal fibrosis." (PMID 40885718, 2025). "In this study, we clarified the mechanism of tamoxifen in alleviating high glucose-induced fibrosis by inhibiting ESR1 transcribing H19 in peritoneal fibrosis." (PMID 37697303, 2023). "Considering the classic nuclear/genomic actions of ESR1 as a transcription factor to control gene expression, we aimed to investigate whether tamoxifen is involved in the modulation of DNA genomic transcription to mitigate peritoneal fibrosis." (PMID 37697303, 2023). "High glucose activates estrogen receptor 1 (ESR1) in PMCs, which induces EMT and peritoneal fibrosis in long term PD." (PMID 40918510, 2025).
polyp (3 papers, 2008 to 2024). A usually exophytic mass attached to the underlying tissue by a broad base or a thin stalk. "This is consistent with observations showing a positive association between RCF and methylation of SFRP1 and ESR1 in the apparently normal mucosa of previous polyp patients." (PMID 23157586, 2013).
Ventricular arrhythmia (3 papers, 2011 to 2022). "In postmenopausal women, carriers of ESR1 haplotype 1 also have a higher risk of death from such events, although it is unknown whether these represent sudden deaths due to ventricular arrhythmias." (PMID 21658281, 2011).
acute liver failure (2 papers, 2012 to 2014). Rapid deterioration of liver function causing encephalopathy and coagulopathy. "Here we examine whether the ESR1 polymorphisms or its haplotypes are related to HBV-related acute liver failure (ALF) risk among chronic HBV carriers in a Chinese population." (PMID 22727021, 2012).
atrial fibrillation (2 papers, 2014 to 2023). A disorder characterized by an electrocardiographic finding of a supraventricular arrhythmia characterized by the replacement of consistent P waves by rapid oscillations or fibrillatory waves that vary in size, shape and timing and are accompanied by an irregular ventricular response. "Our results indicate that a greater number of (TA)n repeats in the promoter region of ESR1 is associated with a significantly increased likelihood of lone atrial fibrillation in men." (PMID 24577825, 2014).
autoimmune myasthenia gravis (2 papers, 2023 to 2024). "In autoimmune myasthenia gravis, which is more frequent in women than in men, the ESR1 gene expressing estrogen receptor α (ERα) and the ESR2 gene expressing estrogen receptor β (ERβ) can mediate multiple physiological effects of estrogen." (PMID 36818231, 2023).
behavioral disorders (2 papers, 2017 to 2023). "Genetic variants of ESR1 have been implicated in multiple diseases, including behavioral disorders, but causative variants remain uncertain." (PMID 28617822, 2017). "The first common ESR1 variant (MAF 12–33% across races) linked to regulatory functions, rs2144025 appears conditionally to affect ESR1 mRNA expression in the brain and modulate traits in behavioral disorders." (PMID 28617822, 2017).
cerebrovascular disease (2 papers, 2020 to 2021). "Some diversities in single nucleotide polymorphisms (SNP) of the ESR1 have different effects on the risk of IS, such as the onset age and the probability of developing cerebrovascular disease." (PMID 34194527, 2021). "An association between variation in the estrogen receptor-alpha gene (ESR1) and cerebrovascular disease is related to gender." (PMID 34194527, 2021).
chondroblastoma (2 papers, 2009 to 2022). A benign, chondroid-producing, well-circumscribed, lytic neoplasm usually arising from the epiphysis of long bones. "However, diffuse expression of SRD5A1, ESR1 and CYP19 in all the chondroblastomas tested, including the index case, was found." (PMID 19903358, 2009).
chondrosarcoma (2 papers, 2011 to 2018). A malignant cartilaginous matrix-producing mesenchymal neoplasm arising from the bone and soft tissue. "Remarkably, the expression of ESR1 was significantly higher in breast cancer associated with chondrosarcoma." (PMID 22613849, 2011). "We observed ESR1 in 73% of the well differentiated and in 84% of the dedifferentiated component of dedifferentiated chondrosarcoma." (PMID 22613849, 2011). "The presence of ESR1 and aromatase in chondrosarcoma tumors and primary cultures supports a possible role of estrogen signaling in chondrosarcoma proliferation." (PMID 22613849, 2011). "All five conventional chondrosarcomas expressed ESR1 and aromatase protein, supporting the rationale of the treatment." (PMID 22613849, 2011). "We observed such a trend in the peripheral chondrosarcomas, where only 33% of the high grade tumors show positive staining for ESR1." (PMID 22613849, 2011). "In our study, in 65% (15 out of 23) of the mesenchymal chondrosarcomas the small cell component was positive for ESR1, while in 33% (5 out of 15) of the tumors also the cartilaginous areas were positive." (PMID 22613849, 2011). "In conventional central and peripheral chondrosarcoma we observed immunoreactivity against ESR1 in 81% (34 out of 42) and 81% (21 out of 26) of the tumors, respectively." (PMID 22613849, 2011). "Previous studies have demonstrated the presence of the ESR1 and activity of aromatase in conventional chondrosarcoma." (PMID 22613849, 2011). "In peripheral chondrosarcoma only 33% of the grade III tumors showed ESR1 expression." (PMID 22613849, 2011). "We have observed ESR1 expression and aromatase expression each in 69% of the clear cell chondrosarcomas, suggesting that also these chondrosarcoma patients potentially might benefit from antiestrogen therapy and/or aromatase inhibition." (PMID 22613849, 2011). "We investigated the protein expression of estrogen receptor alpha (ESR1), androgen receptor (AR), and aromatase in tumor specimens of various chondrosarcoma subtypes, and (primary) chondrosarcoma cultures." (PMID 22613849, 2011). "In that study, ESR1 and CYP19A1 mRNA expression were demonstrated in a set of 23 conventional chondrosarcomas and 7 (primary) chondrosarcoma cultures." (PMID 22613849, 2011). "In addition, ESR1 and ESR2 expression has been shown to be a common phenomenon in chondrosarcomas." (PMID 22613849, 2011). "However, all their mesenchymal chondrosarcoma cases were ESR1 negative." (PMID 22613849, 2011).
dental fluorosis (2 papers, 2022 to 2025). A condition that results from excessive fluoride ingestion during tooth development, resulting in tooth discoloration ranging from white streaks to brown stains and cracks or pits in the tooth enamel. "Within this subset, polymorphisms in DLX3 (rs2278163) and ESR1 (rs12154178) are associated with fluorosis severity, indicating a role in modulating the phenotypic expression of enamel defects." (PMID 41174690, 2025). "Dental fluorosis is linked to human ESR1 because estrogen or its receptors affect the activity of ameloblasts, which directly leads to the development of dental fluorosis." (PMID 36557738, 2022). "The overdominant model for ESR1 rs12154178 showed a statistically significant association: individuals with the C/A genotype had lower odds of presenting moderate fluorosis than those with homozygous genotypes (C/C + A/A) did (OR = 0.31, 95% CI: 0.10–0.95; p = 0.034)." (PMID 41174690, 2025). "Additionally, a significant association was identified between the recessive model of the rs2278163 DLX3 and rs12154178 ESR1 polymorphisms and mild and moderate fluorosis (p = 0.02, OR = 0.25, 95% CI: 0.07–0.88 and p = 0.034, OR = 0.31, 95% CI: 0.10–0.95, respectively)." (PMID 41174690, 2025). "Indeed, our results revealed polymorphisms in DLX3 and ESR1 that were more common in individuals with mild fluorosis, suggesting that these SNPs may act as protective factors, reducing the likelihood of severe enamel alteration even in the context of elevated fluoride exposure." (PMID 41174690, 2025). "Therefore, this study aimed to investigate whether ESR1 rs12154178 and ESR2 rs1256049 polymorphisms are associated with the severity of dental fluorosis in pregnant women from Durango, Mexico." (PMID 41174690, 2025). "The universal presence of fluorosis in this cohort, coupled with the limited number of severe cases and the identification of potentially protective genotypes in DLX3 and ESR1, suggests that genetic variation plays a meaningful role in modulating individual susceptibility." (PMID 41174690, 2025).
estrogen resistance (2 papers, 2023 to 2024). "Recent reports suggest impaired glycemic homeostasis was observed in men with estrogen resistance and mutation in ESR1 and CYP19A1." (PMID 38001940, 2023). "All suggested estrogen resistance syndrome and were in accordance with the reproductive phenotype of Esr1 ubiquitous knockout mouse models described in section 4.1.1." (PMID 38978624, 2024).
folate deficiency (2 papers, 2015 to 2017). A nutritional condition produced by a deficiency of FOLIC ACID in the diet. "Previous studies demonstrated that folate deficiency affected the gene expression of Esr1, Cav1, and Elavl1." (PMID 28445960, 2017). "To investigate the effect of folate deficiency on the methylation status of the ESR1, CAV1 and ELAVL1 promoters, we selected 20 semen samples with low ( < 25th percentile) and high (> 75th percentile) folate concentrations." (PMID 28445960, 2017). "In addition, folate deficiency can evidently reduce the gene expression levels of ESR1, CAV1 and ELAVL1, which are critical to spermatogenesis." (PMID 28445960, 2017).
gonadotroph adenoma (2 papers, 2022). "In the SF-1 lineage, the ROC value of CHST7 was better than that of either ESR1 or SF-1, which were adopted as classification indices for gonadotroph adenoma in the 2017 WHO classification." (PMID 35954244, 2022).
hypertrophic cardiomyopathy (2 papers, 2008 to 2025). A condition in which the myocardium is hypertrophied without an obvious cause. "Also, a recent study of patients with hypertrophic cardiomyopathy demonstrated polymorphisms in the estrogen receptor alpha (ESR1) gene, as well as in the androgen receptor (AR) gene to be associated with left ventricular wall thickness in men, but not in women." (PMID 19077249, 2008). "Altered DNA methylation profile was observed in hypertrophic cardiomyopathy which affected altered genes such as ITLN1 related to immune function where ESR1 gene is at its node." (PMID 40406098, 2025).
hyperuricemia (2 papers, 2021 to 2022). An abnormally high level of uric acid. "Among them, ESR1 has the most frequent gene connections (D = 36), followed by ALB (D = 24) and APOA1 (D = 11), indicating their key roles in both hyperuricemia and HFrEF." (PMID 35911515, 2022). "The core targets of Plantaginis Herba for the treatment of hyperuricemia were AKT1, mitogen-activated protein kinase 3 (MAPK3), MAPK1, tumor necrosis factor (TNF), prostaglandin-endoperoxide synthase 2 (PTGS2), sirtuin 1 (SIRT1), estrogen receptor 1 (ESR1), and androgen receptor (AR)." (PMID 33897800, 2021).
Inguinal hernia (2 papers, 2025). Protrusion of the contents of the abdominal cavity through the inguinal canal. "Multiomics analyses of in vitro LAM fibroblasts from humanized mice unveiled an estrogen/ESR1-mediated activation of a distinct profibrotic cistrome and gene expression signature, concordant with observations in inguinal hernia tissues in human males." (PMID 39903526, 2025). "Activation of estrogen receptor-alpha (ESR1) in mouse fibroblasts within lower abdominal muscles stimulates fibrosis, leading to inguinal hernias, which can be fully reversed by inhibiting the ESR1 pathway." (PMID 39903526, 2025). "In our study, the direct induction of both FBLN7 and FBLN3 by E2/ESR1 amplifies the potential applicability of these findings across a broad spectrum of inguinal hernias." (PMID 39903526, 2025). "E2/ESR1-modulated mRNA or protein expression in Aromhum LAM is comparable to that observed in men with inguinal hernias." (PMID 39903526, 2025). "Overall, our findings demonstrate that the activation of E2/ESR1 signaling in LAM fibroblasts from a large subset of men with inguinal hernias is similar to that observed in HAFs from Aromhum mice, emphasizing the clinical relevance of E2/ESR1 signaling in inguinal hernias in men." (PMID 39903526, 2025). "We also sought to determine whether the positive correlation between ESR1 expression, PGR expression, and fibroblast proliferation was present in the abdominal muscle of human patients with inguinal hernias." (PMID 40504614, 2025). "However, the necessity and role of E2/ESR1 signaling in the LAM and inguinal hernia formation remained unclear." (PMID 39903526, 2025).
intervertebral disc degeneration (2 papers, 2022 to 2025). "CirC-0040039 may promote apoptosis of nucleus pulposus cells and aggravate intervertebral disk degeneration by inhibiting ESR1 expression and promoting miR-874-3p." (PMID 35619068, 2022).
intrahepatic cholangiocarcinoma (2 papers, 2021 to 2022). A carcinoma that arises from the intrahepatic bile duct epithelium in any site of the intrahepatic biliary tree. "The inhibition of ESR1 was found to be significantly associated with the recurrence and progression of intrahepatic cholangiocarcinoma." (PMID 36467100, 2022).
intrahepatic cholestasis (2 papers, 2022 to 2025). A cholestasis characterized by impairment of the bile flow caused by obstruction located in the liver. "We validated the changes in 5 out of 7 core putative targets in the treatment of DCHT for ANIT-induced intrahepatic cholestasis, with the exception of estrogen receptor (ESR) 1 and 2 (ESR1 and ESR2) because they are more associated with intrahepatic cholestasis during pregnancy." (PMID 35370715, 2022).
kidney stone (2 papers, 2022 to 2023). "Our findings suggest that BSHS may inhibit kidney stone formation mainly by regulating estrogen and estrogen receptor levels, inhibiting oxidative stress processes, reversing apoptosis, and decreasing CaOx crystals deposition through E2/ESR1/ESR2, NRF2/HO-1, and BCL2/BAX signaling pathways." (PMID 36864834, 2023).
liver failure (2 papers, 2012 to 2019). A liver disease characterized by the liver losing or has lost all of its function. "It is also interesting to investigate whether the ESR1 intron region polymorphisms are associated with alcohol and drug induced liver failure in the west countries, where alcohol consumption and drug use are more popular." (PMID 22727021, 2012).
malignant mesothelioma (2 papers, 2016 to 2020). A malignant neoplasm of the pleura or peritoneum, arising from mesothelial cells. "One recognizes malignant mesothelioma as ER negative and another reports a statistically significant enhancement of estrogen receptor 1 (ERS1) methylation in malignant mesothelioma compared to non-tumour lung samples." (PMID 27323398, 2016).
Mayer-Rokitansky-Küster-Hauser syndrome (2 papers, 2019 to 2023). "DNA sequence analyses of both OXTR and the estrogen receptor 1 gene (ESR1) in patients with Mayer-Rokitansky-Küster-Hauser syndrome were performed." (PMID 36835321, 2023).
metaplastic breast carcinoma (2 papers, 2013 to 2022). A group of invasive breast carcinomas characterized by the presence of an adenocarcinomatous component which is admixed with a dominant component that is composed of squamous cells, spindle cells, or mesenchymal cells. "ESR1-LBD was absent or poorly expressed in non-malignant breast tissue but found to variable levels in ERα(+) tumors, TNBC, and metaplastic breast cancers (MpBC)." (PMID 35999225, 2022).
ovarian serous cystadenocarcinoma (2 papers, 2019 to 2024). A malignant serous cystic epithelial neoplasm arising from the ovary. "On the other hand, breast invasive carcinoma (BRCA) and ovarian serous cystadenocarcinoma (OV) showed increased expression of ESR1 RNA." (PMID 38666956, 2024). "MME, SOX17, AGTR1, PGR, and ESR1 had the highest amplifications frequency ranging from 4% to 11% in ovarian serous cystadenocarcinoma." (PMID 31879572, 2019).
Primary amenorrhea (2 papers, 2018 to 2019). "In women, ESR1 deficiency was associated with clinical features of estrogen resistance, including primary amenorrhea, the absence of breast development, a small uterus and enlarged multicystic ovaries." (PMID 31745224, 2019).